NLRP3 (NLR family pyrin domain containing 3)
Diseases named in the same sentence as NLRP3 in open-access papers (continued):
Sharing a sentence is not in itself a finding about the gene and the disease.
cancer (continued). "Several literatures have shown that the NLRP3 inflammasome orchestrates cancer pathogenesis by governing cell death pathways." (PMID 31492049, 2019). "In the last years, some authors have demonstrated the implication of NLRP3 inflammasome in tumorigenesis and cancer development, specifically in basal cell carcinomas." (PMID 31374828, 2019). "Our study revealed that the expressions of NLRP3 in ccRCC cancer tissues were significant lower than that in normal kidney tissues for the first time." (PMID 30770793, 2019). "Another crucial issue concerns the rick of adverse reactions following full inhibition of NLRP3, such as cancer observed in NLRP3-/- mice." (PMID 31200447, 2019). "Another study showed that the NLRP3 inflammasome was correlated with the carcinogenesis and development of cancer stem cells (CSCs) in HNSCC." (PMID 31492049, 2019). "In contrast, the ability to induce the cancer cell migration was dramatically reduced when conditioned media from ATP-stimulated NLRP3 KO macrophages was added (WT, ATP vs KO, ATP: 553.8 ± 130.09 vs 214.6 ± 59.07)." (PMID 31439870, 2019). "The findings reported in previous studies also support the findings in the present paper; NLRP3 inflammasome expression is higher in cancer tissues than adjacent normal tissues in other types cancers." (PMID 31312615, 2019). "Results from a GeneMANIA database analysis showed that PLCG2, CHI3L2, SH2D2A, and NLRP3 and 20 other proteins formed a complex network of which 12 genes were enriched in cancer-related pathways." (PMID 31993418, 2019). "The results showed that the mRNA expression of the NLRP3 inflammasome markedly increased in the cancer tissues compared to the adjacent normal tissues (P < 0.001)." (PMID 31312615, 2019). "Several studies have elucidated the relationship between NLRP3 inflammasome signaling and carcinogenesis, that NLRP3 inflammasome inhibition is responsible for cancer prevention." (PMID 31412862, 2019). "NLRP3 inflammasome expression was validated using RT-qPCR experiments to study the mRNA levels of the NLRP3 inflammasome in cancer tissues and the corresponding adjacent normal tissues from another cohort of 20 LSCC patients." (PMID 31312615, 2019). "As expected, macrophage depletion by LEC following urethane injection significantly decreased lung tissue injury and carcinoma lesions accompanied by a reduction in NLRP3 inflammasome." (PMID 30984004, 2019). "The most studied inflammasome is the NLRP3 inflammasome, and mounting evidences support that the NLRP3 inflammasome plays an important role in the development of malignant tumors." (PMID 30211233, 2018). "Previous studies indicated that the effects of NLRP3 inflammasome are complex with differential roles in different types of cancers." (PMID 29716544, 2018). "Mice models with NLRP3, caspase-1 and ASC adaptor deficiencies show protection against cancer progression." (PMID 30447690, 2018). "Asbestos induces NLRP3 inflammasome activation in mesothelial cells leading to an inflammatory response and eventually cancer initiation and progression." (PMID 30447690, 2018). "In most of the reports cited, the evidence suggesting that the NLRP3 inflammasome is contributing to cancer progression in vivo remains preliminary and requires further confirmation." (PMID 30447690, 2018). "NLRP3 inflammasome activation plays an important role in the proliferation, survival, migration or invasiveness of many cancer cells." (PMID 29874795, 2018). "Previous studies indicate that NLRP3 inflammasome exerts diverse and sometimes contrasting roles in the development of different cancers including lung cancer." (PMID 30560887, 2018). "Further substantiating the role of inflammasomes in the immunobiology of cancer is the significantly higher activation of NLRP3 inflammasome observed during chemotherapy treatment." (PMID 30631327, 2018).
cancer (continued). "In this review, we summarize the current knowledge on the contribution of the NLRP3 inflammasome on potential cancer promotion and therapy." (PMID 30447690, 2018). "Downregulated expression of NLRP3 inflammasome in HCC tissues correlates with the aggravation of carcinoma, while reconstitution of NLRP3 inflammasome dramatically reverses the malignant phenotype of HCC." (PMID 30319645, 2018). "NLRP3 inflammasome plays a key role in inflammation, and recent evidence showed that activation of NLRP3 inflammasome was correlated with carcinogenesis and progression in cancers." (PMID 28865486, 2017). "Our results showed that the cancer expression of stem cell markers BMI1, ALDH1 and CD44 were highly upregulated in human SCCHN and mice SCCHN tissues, and NLRP3 inflammasome was closely associated with those makers." (PMID 28865486, 2017). "NLRP3, as part of the inflammasome protein complex, is better characterized in cancer compared with the others." (PMID 28637493, 2017). "Activated NLRP3 inflammasome induces the maturation of its effector cytokine IL-18 which functions in the development of cancer." (PMID 29312552, 2017). "NLRP3 inflammasome is an emerging key player in the development and progression of cancers, but its role in tumorigenesis and stimulating antitumor immunity are complex." (PMID 28865486, 2017). "Sphere-forming assay and colony formation assay were performed to investigate the potential role of NLRP3 inflammasome in the self-renewal capacity of cancer cells." (PMID 28865486, 2017). "We found that both P2X7R and NLRP3 inflammasome component expression were upregulated in cancer tissues compared to normal tissues." (PMID 28430665, 2017). "Although several lines of evidence have indicated the pro-carcinogenic activities of NLRP3, its role in cancer development remains controversial." (PMID 27206676, 2016). "Together, these observations indicated that an induction of hypoxia in PC-3 cancer cells primed cells and spontaneously activated NLRP3 inflammasome activity." (PMID 27058421, 2016). "Accordingly, gemcitabine and 5-fluorouracil exert increased antitumor effects when tumors were established in NLRP3−/− or Caspase-1−/− mice, and NLRP3 activation by chemotherapeutic drugs is considered to be a positive regulator to promote cancer growth." (PMID 27206676, 2016). "The variability in NLRP3- and IL-18-mediated effects in different cancers highlights the complexity in NLR circuits and suggests that any broad implications regarding NLR intervention in tumorigenesis should be carefully investigated." (PMID 25071785, 2014). "NLRP3 inflammasome plays an important role in the development of many cancer types, including melanoma, intestinal cancer, nasopharyngeal carcinoma, skin cancer, colorectal cancer." (PMID 24587153, 2014). "Human monocytic THP-1 cells overexpressing a mutant variant of NLRP3 bearing the Q705K SNP have been reported to greatly respond to the inflammasome agonist alum and to trigger the production of IL-1β and IL-18, implying that overt NLRP3 activation could be detrimental for certain types of cancer." (PMID 25071785, 2014). "As inflammation has been shown to be both beneficial and detrimental for cancer, it is fitting that NLRP3 activation in immunotherapy can also be beneficial and detrimental." (PMID 24273542, 2013). "Danger signals released from dying cells have been shown to activate the NLRP3 inflammasome and it is possible that cancer cells release specific ligands capable of activating other NLRs." (PMID 24273542, 2013). "NLRP3-inflammasome is known to play an important role in cancer cell transformation and in the immune response against tumors and has been described as the intracellular sensor of asbestos." (PMID 23031505, 2012). "In particular we will discuss how cancer cells dying via autophagy trigger ATP-dependent NLRP3 inflammasome activation in the macrophages engulfing them, eliciting an immunogenic response against tumors." (PMID 23316199, 2012).
cancer (continued). "NLRP3, a key inflammatory mediator, connects immunity and cancer." (PMID 41003004, 2025). "these seemingly contradictory functions of NLRP3 inflammasome in tumors may be temporal, contextual, tissue, and cancer specific." (PMID 40671401, 2025). "Furthermore, targeting NLRP3, which affects several IL-1-mediated chronic diseases, including cancer and cardiometabolic and neurodegenerative diseases, is a promising approach since orally available inhibitors have been developed." (PMID 41087719, 2025). "For example, the NLRP3 inflammasome has been shown identified as a negative regulator of tumorigenesis in colitis-associated cancer." (PMID 40692785, 2025). "Similarly, the role of inflammasomes, particularly NLRP3, in cancer has been increasingly recognized, linking inflammation directly to cancer progression." (PMID 40034825, 2025). "Finally, in the context of cancer, curcumin has been shown to induce NLRP3-dependent pyroptosis by targeting Smurf2, an E3 ubiquitin ligase that mediates NLRP3 degradation." (PMID 40806716, 2025). "While information on the anti-cancer role of NLRP3, nothing is known regarding AIM2 inflammasome." (PMID 39857785, 2025). "Therefore, understanding the mechanism and consequences of NLRP3 inflammasome activation in cancer is critical for developing novel therapeutic strategies." (PMID 41560727, 2025). "However, when the macrophages were incubated with the CM from cancer cells that had been pre-treated with LpOC01-SN, we observed a marked increase in NLRP3 and ROS levels." (PMID 40002754, 2025). "Then, sumerized the NLRP3 inflammasomes' function of inflammatory diseases and cancer." (PMID 40671401, 2025). "To further investigate whether NLRP3 influences cancer‐related lymphangiogenesis, we analyzed the relationship between NLRP3 and lymphatic vessel formation." (PMID 40135589, 2025). "Similar to AIM2 and NLRP3, NLRC4 is implicated in various types of cancer." (PMID 40692785, 2025). "Therefore, the combination therapy of NLRP3 inhibitors is anticipated to become a potential direction for future cancer treatments, including breast cancer." (PMID 40830103, 2025). "Further clinical trials and extended studies are warranted to fully elucidate the safety, efficacy, and potential broader applications (eg. cancer, neuroinflammation) of these promising NLRP3 inhibitors, laying the foundation for their translation into novel therapeutic interventions." (PMID 39653810, 2025). "A similar duality in NLRP3 function is observed in certain cancers." (PMID 41062723, 2025). "However, excessive activation of NLRP3 inflammasome can also lead to a hyper‐inflammatory state, ultimately leading to auto‐inflammatory disease, neurodegenerative disease, and cancer progression." (PMID 40671401, 2025). "Therefore, BETis originally identified as inducers of cancer cell death act unexpectedly to block NLRP3-driven pyroptosis and, at least in macrophages, are relatively specific to this particular cell death pathway." (PMID 40632844, 2025). "This study underscores that NLRP3 not only orchestrates innate immune sensing but also acts as a molecular switch controlling adaptive immune plasticity, redefining its relevance in the evolving crosstalk between inflammation and cancer immunity." (PMID 41291696, 2025). "When compared to the control medium, the conditional media of lamin-deficient cancer cells did not change NLRP3 inflammasome and STING/TBK1 pathways in macrophage cells." (PMID 40708945, 2025). "As a key factor in pyroptosis, the role of NLRP3 in cancer has been widely investigated." (PMID 39951856, 2025). "In this review, we focus on and discuss the role of the NLRP3 inflammasome in cardiovascular diseases induced by radiotherapy and how its modulation could represent a potential therapeutic target to improve cancer survivors’ quality of life." (PMID 41272654, 2025).
cancer (continued). "Similarly, other cancer types have also been reported to express high levels of NLRP3 and to secrete IL-1β, which strongly correlates with disease progression." (PMID 39858071, 2025). "In conclusion, SOAT1 could promote OSCC malignancy and regulate the activation of NLRP3 inflammasome to increase the rate of lymphangiogenesis and cancer metastasis via IL‐1β/IL‐1R‐1 axis in OSCC." (PMID 40135589, 2025). "Therefore, understanding the mechanisms and consequences of NLRP3 inflammasome activation in cancer is critical for developing novel therapeutic strategies." (PMID 41560727, 2025). "Agonists of the cytosolic double-stranded DNA-sensing stimulator of IFN gene (STING) pathway can mediate proinflammatory conversion of cancer MDSCs; however, secretion of the NLRP3 products IL-1β and IL-18 has also been observed in certain myeloid populations following STING activation." (PMID 40377974, 2025). "Moreover, investigations have confirmed that elevated NLRP3 levels are among the critical factors contributing to the growth and metastasis of cancer cells in various malignancies, such as lung carcinoma." (PMID 40830103, 2025). "Therefore, the NLRP3 inflammasome represents a key player in cancer development, and its regulation by miRNAs highlights its importance and clinical potential." (PMID 41560727, 2025). "They correlated the levels of CSC (cancer stem cell) markers with NLRP3 inflammasome and concluded that NLRP3 promotes CSC formation and might play a role in regulation of CSCs in HNSCC." (PMID 41410801, 2025). "In this study, we investigated the role of NLRP3 in Th17 cells in the context of cancer." (PMID 40195474, 2025). "Additionally, the GSDMD pathway, triggered by NLRP3 activation, can induce pyroptosis in cancer cells, thereby suppressing cancer growth and invasion." (PMID 40718836, 2025). "Thus, we first analyzed the co-expression profiles of FLT3 and NLRP3 using the TCGA Pan-Cancer data via UCSC Xena." (PMID 39875995, 2025). "Collectively, these approaches may help unravel the molecular, cellular, and contextual determinants of NLRP3 signaling and could guide the development of safer, context-specific therapeutic interventions for infections, autoinflammatory diseases and cancer." (PMID 41062723, 2025). "In conclusion, specific inflammatory molecular pathways, particularly those related to the NLRP3 inflammasome, may serve as common therapeutic targets for both cancer and HF." (PMID 40069106, 2025). "In OSCC, the NLRP3 inflammasome promotes proliferation, migration and invasion of cancer cells." (PMID 40692785, 2025). "Additionally, the roles and mechanisms of specific immunometabolites should be investigated in the context of the NLRP3 inflammasome-related pathogenesis of disease conditions, such as cancer." (PMID 40307577, 2025). "Moreover, as the mediator of lymphocytes and macrophages as well as a predictive biomarker of cancer immunotherapy response, NLRP3 inflammasome has shown its prognostic and therapeutic potentials." (PMID 40135589, 2025). "In addition to NLRP3 being implicated in chronic inflammation and cancer progression, the dsDNA-sensing PRRs, AIM2 and IFI16, have been involved in oral diseases and cancer." (PMID 41440367, 2025). "Inflammasomes, particularly the NLRP3 inflammasome, play complex and dual roles in cancer immunity." (PMID 40155968, 2025). "Future investigations could delve into the intricate relationship between IL-1β levels and cancer progression, providing a theoretical basis for the development of drugs modulating NLRP3 inflammasome." (PMID 38317229, 2024). "The NLRP3 inflammasome plays a central role in the pathogenesis of several cancers." (PMID 39301197, 2024). "NLRP3 inflammasomes are closely related to the proliferation of cancer." (PMID 38182564, 2024). "Therefore, further investigations are required to understand the mechanisms through which the NLRP3 inflammasome regulates cancer growth and progression." (PMID 39769450, 2024).
cancer (continued). "It has been suggested that NLRP3 inflammasome signaling is related to carcinogenesis and that suppression of NLRP3 inflammasome could serve as a cancer prevention strategy." (PMID 39075259, 2024). "Some emerging evidence suggested that NLRP3 may also be a potent target in PANoptotic cancer therapy." (PMID 38553639, 2024). "Specifically, PPARα directly binds to the lncRNA Gm15441 promoter to upregulate its expression and attenuate hepatic inflammation by decreasing the NLR family pyrin domain containing 3 (NLRP3) inflammasome activation, which is known to play important roles in cancer." (PMID 39199690, 2024). "In fact, the inhibition of NLRP3 expression reduced the migratory and invasive capacities of cancer cells, whilst also inverting the mesenchymal condition by reducing vimentin and Matrix metalloproteinase-9 (MMP9) expression and increasing E-cadherin expression." (PMID 39684769, 2024). "The NLRP3 inflammasome promotes the immune system to fight microbial infection, however, aberrant NLRP3 inflammasome activation can contribute to the pathogenesis of several autoinflammatory disorders, cancer, metabolic, and aging-related diseases." (PMID 38789414, 2024). "Further studies, such as quantitative analysis, are needed to clarify the use of Gal-3 and NLRP3 expression as new markers that may indicate a pro-inflammatory state during chronic inflammatory diseases and cancer transformation." (PMID 38172822, 2024). "Additional factors, including Doublecortin-like kinase 1 (DCLK1) isoform 2, a member of the regenerating islet-derived family REG4, NLR family pyrin domain containing 3 (NLRP3), and Notch signaling pathways, also play roles in enhancing M2 polarization and have potential roles in cancer progression." (PMID 38891952, 2024). "Besides various infectious and inflammatory complications, recent studies also indicated the significance of NLRP3 inflammasome in cancer progression and therapy." (PMID 39769450, 2024). "In addition, the instigation of the NLRP3 inflammasome by LPS and ATP upregulated cancer stem cell characteristics and induced sphere-forming and colony formation abilities." (PMID 38904007, 2024). "However, there are different opinions about the effect of NLRP3 on the cancerization process in cancer cells." (PMID 38543085, 2024). "It has been postulated that silencing of the ASC gene, a core component of the NLRP3 inflammasome, may have a role in cancer cell survival." (PMID 39516433, 2024). "Furthermore, a positive correlation has been observed between elevated levels of NLRP3 expression and malignant tumors, distant metastasis, vascular invasion, and lymph node positivity." (PMID 38892354, 2024). "Whilst the NLRP3 inflammasome has not been investigated in OC, it has been implicated in numerous cancers." (PMID 39516433, 2024). "Additionally, it activates TLR4, enhancing the expression of NLRP3 and promoting the secretion of chemotactic factors and inflammatory mediators from the cancer cells." (PMID 39610830, 2024). "According to a previous study, an intrinsic stimulus, such as oncogene-induced reactive oxygen species, could serve as the second stimulus for NLRP3 activation in cancer cells." (PMID 38543085, 2024). "Our results suggest a prominent role of neutrophil NLRP3 for neutrophil homing and could have broad implications for various diseases, including cancer therapy, and should be investigated further in more detail." (PMID 38914598, 2024). "The role of NLRP3 is well-described in immunological cells, mainly macrophages, neutrophils, monocytes, and dendritic cells, in various immunological diseases, including cancer." (PMID 38543085, 2024). "Aberrant NLRP3 activation has been demonstrated to participate in the progression of several pathological conditions from neurogenerative diseases to cardio-metabolic syndromes and cancer." (PMID 39188718, 2024).